ATM (ATM serine/threonine kinase)
Diseases named in the same sentence as ATM in open-access papers (continued):
Sharing a sentence is not in itself a finding about the gene and the disease.
Ewing sarcoma (10 papers, 2012 to 2025). A small round cell tumor that lacks morphologic, immunohistochemical, and electron microscopic evidence of neuroectodermal differentiation. "In this study, combination treatments of the HSP90 inhibitor AUY922 with either the ATR inhibitor VE821 or the ATM inhibitor KU55933 were investigated for their effectiveness in Ewing's sarcoma cells." (PMID 33743824, 2021). "Increased sensitivity to DNA damaging agents in Ewing sarcoma can be explained by defective DNA break repair and down regulation of DNA repair genes BRCA1, GEN1, and ATM." (PMID 27248664, 2016).
lymph node metastasis (10 papers, 2015 to 2025). "ATMMUT alone or ATM co-mutations were significantly positively correlated with lymph node metastasis." (PMID 38886866, 2024). "Overexpression of ATM has been associated with lymph node metastasis, while inhibition of ATM has been described to reduce cell migration and invasion." (PMID 34204447, 2021). "As such, we hypothesize that the ATM mutation may be the trigger for higher TMB levels in MSS lymph node metastases." (PMID 34707195, 2021). "The homologous recombination repair gene ATM existed in all three pathways and correlated with lymph node metastasis." (PMID 38886866, 2024). "Mutated genes associated with lymph node metastasis in the univariate analysis, including RET, ATM, PIK3CA, TERT, GGT1 and fusions, were incorporated to construct a gene signature model." (PMID 38886866, 2024). "Low expression of ATM was observed frequently in samples with ATMMUT and was significantly associated with lymph node metastasis." (PMID 38886866, 2024). "Majority of the ATM mutant cases were larger tumors (T3/T4–83.3%; 5/6), had lymph node metastasis (66.7%; 4/6), were advanced stage (Stage III/IV–50%; 3/6) and hormone receptor positive (83.3%; 5/6)." (PMID 38017116, 2023). "When comparing the molecular landscape of TMB-high lymph node metastases and other tumor locations, ATM genetic alterations were observed more frequently in the TMB-high lymph node metastases group." (PMID 34707195, 2021). "Given the median number of mt/Mb, TMB-high lymph node metastases showed a higher frequency of ATM (13.3% vs 2.6%, p = 0.003) and NRAS (5.7% vs 0.9%, p = 0.04) mutations and more commonly manifested overexpression of PD-L1 (7.9% vs 0.9%, p = 0.014)." (PMID 34707195, 2021). "Clinicopathological features, including differentiation stages, distant metastasis, lymph node metastasis, T classification, TNM stage, and tests of thyroid functions (TPOAb, Tg Ab, T3, FT3, T4, FT4, TSH, and Tg), were reviewed and their associations with γH2AX and ATM were analyzed." (PMID 25861265, 2015).
meningioma (10 papers, 2013 to 2025). A generally slow growing tumor attached to the dura mater. "Prior studies have demonstrated that there is a relationship between meningiomas and mutations in ATM." (PMID 36514795, 2022). "To date, the present study is the largest to report on the association of ATM and elevated risk of meningioma recurrence." (PMID 36514795, 2022). "Although a slight increase of an ATM haplotype frequency has been reported in meningioma compared to control population, this is the first reported case of meningioma developing in a patient with an ATM germline cancer-predisposing mutation." (PMID 31963394, 2020). "We identified NF2 mutations, chromatin remodeling and DDR gene mutations as independent prognostic markers for aggressive course, and described the first case of meningioma developing in a patient with ATM germline cancer-predisposing mutation." (PMID 31963394, 2020). "In summary, this study provided evidence that p14ARF, RASSF1A, p15INK4B (CDKN2B), RUNX3, GATA6, p16INK4A (CDKN2A), NDRG2 and to lesser extent ATM and RARβ promoter methylation are associated with the development of meningiomas." (PMID 25648363, 2015). "The detection of a germline pathogenic mutation in ATM in a patient from ED group #3 with aggressive disease course is the first evidence that, in addition to other neoplasms, heterozygous ATM mutations also predispose to meningioma." (PMID 31963394, 2020). "D1853N polymorphism of ATM gene was mosaics in two patients with meningiomas." (PMID 31565199, 2019). "We revealed specific signatures in lower-grade meningioma such as NF2, AKT1E17K, and KLF4K409Q, and identified co-occurring mutations such as ATM-BIVM-ERCC5, PIK3C2B-SDHD, and ERCC4-MET." (PMID 40562609, 2025). "Further study is warranted to determine if ATM mutant meningiomas would garner an outsized survival benefit from treatment with such an agent or radiation protocol." (PMID 36514795, 2022). "Then, excluding B2M and ATM, regarding the other mutations found in the other genes, no definitive conclusions can be drawn about their role in the development of meningioma due to the lack of previous evidence." (PMID 40725113, 2025). "First, a specific germline ATM haplotype is over-represented in patients with meningiomas." (PMID 36514795, 2022). "Another study demonstrated that ATM mutant Grade II meningiomas display poor long-term outcomes." (PMID 36514795, 2022). "The aim of this study was to evaluate the methylation status of 12 cancer-related genes, namely ERCC1, hMLH1, ATM, CDKN2B (p15INK4B), p14ARF, CDKN2A (p16INK4A), RASSF1A, RUNX3, GATA6, NDRG2, PTEN, and RARβ, in 44 meningioma samples of WHO grade I and II." (PMID 25648363, 2015).
rectal cancer (10 papers, 2013 to 2023). A primary or metastatic malignant neoplasm that affects the rectum. "Accordingly, we previously showed that elevated MRE11 in combination with ATM and MRN complex members was associated with poor outcomes in rectal cancer patients who received neoadjuvant therapy." (PMID 37173905, 2023). "In past studies, we further found that elevated combined expression of MRE11 and ATM or of the entire MRN complex in the TC is associated with a worse prognosis and poor response to neoadjuvant radiotherapy in rectal cancer patients." (PMID 37173905, 2023). "It has been reported that high expression of ATM, especially when combined with MRE11, is associated with worse DFS in rectal cancer treated with neoadjuvant radiotherapy." (PMID 36552003, 2022). "Three frameshift variants including two novel variants (c.907delA in APC gene and c.6743dupA in ATM) and one previously reported mutation (c.657_661delACAAA in NBN) were detected in one patient (male, Kazakh) at the age of 40 with rectum cancer." (PMID 31428572, 2019). "We investigated the combined expression of MRE11 and ATM as a predictive marker of response to radiotherapy in rectal cancer." (PMID 27930716, 2016). "MRE11 and ATM expression were examined in tumor samples from 262 rectal cancer patients who underwent surgery for rectal cancer, including a sub-cohort of 54 patients who were treated with neoadjuvant radiotherapy." (PMID 27930716, 2016). "Overall, our findings suggest that the optimal management of rectal cancer requires tailored treatment based on biomarker expression such as the two-protein MRE11/ATM panel described here, as well as clinicopathologic characteristics." (PMID 27930716, 2016). "No previous studies have compared radiosensitization by AZD7762 and other inhibitors, and we found that it is a better radiosensitizer of rectal cancer cells than inhibitors of other proteins involved in the response to genotoxic agents, as well as other inhibitors of the ATM-Chk1/2 pathway." (PMID 24349411, 2013). "In rectal cancer tissues, expression of miR-18a and ATM correlated inversely." (PMID 23437304, 2013). "Taken together, these results do not support a predictive role of ATM in selecting patients’ sensitivity to radiotherapy in rectal cancer as shown in other neoplasms." (PMID 36552003, 2022). "As a corollary, we proposed that ATM and MRE11 might be used as a predictive marker of radiosensitivity in rectal cancer patients, which would correlate with improved patient outcomes." (PMID 27930716, 2016). "We found that other drugs targeting ATM-Chk1/2 are not as good as AZD7762 at radiosensitizing rectal cancer cell lines." (PMID 24349411, 2013).
renal cell carcinoma (10 papers, 2015 to 2025). "Within Group 2b cases, we confirmed the origin of two relevant TGVs: one germline ATM variant in a patient with papillary thyroid cancer and one somatic BAP1 variant in a patient with renal cell carcinoma." (PMID 39885482, 2025). "In addition, in renal cell carcinoma cells, apigenin caused DNA damage in ACHN cells in a time- and dose-dependent manner and induced G2/M phase cell cycle arrest through ataxia telangiectasia mutated (ATM) signal modulation." (PMID 29034071, 2017). "The NR5A1-derived tumors showed 657 unique proteins that participate in Renal cell carcinoma (CRK, ELOB and PAK3) and Homologous recombination (ATM, BRCC3 and MRE11) among others." (PMID 33261069, 2020). "As expected, AHR is the most enriched pathway in this analysis, followed by pathways of oxidative stress, renal cell carcinoma, Hippo and non-Hippo, ATM dependent DNA damage, and lipid metabolism for LDL, HDL and TG." (PMID 37151890, 2023).
Cerebellar atrophy (9 papers, 2021 to 2025). Cerebellar atrophy is defined as a cerebellum with initially normal structures, in a posterior fossa with normal size, which displays enlarged fissures (interfolial spaces) in comparison to the foliae secondary to loss of tissue. "Progressive cerebellar atrophy was associated with progressive ataxia only in four cases (40%; ATM, CACNA1A, FXN, and SAMD9L)." (PMID 40326640, 2025). "The study by Concannon and Gatti revealed substantial diversity in ATM gene mutations, which were associated with variable degrees of cerebellar atrophy and neurological symptoms." (PMID 41451872, 2025). "For example, mutations in the upstream DNA damage sensor protein ATM result in movement and coordination dysfunction, cerebellar atrophy, and speech impairments." (PMID 33964983, 2021). "However, it remains unclear whether this function is relevant for postmitotic neurons and underlies cerebellar atrophy, since ATM is cytoplasmic in postmitotic neurons." (PMID 37830614, 2023). "Brain MRI revealed cerebellar atrophy in only 1/17 of those tested (patient 28), who was compound heterozygous for p.V2716A and p.Lys119 in the ATM gene." (PMID 40565533, 2025). "Those genes may be potential therapeutic targets for cerebellar atrophy in A–T patients on one hand, as well as biomarkers for cancer resistance to ATM inhibitors on the other." (PMID 37296624, 2023). "Of note, three patients were found to have pathogenic variants in the ATM and SAMD9L genes but did not display evidence of cerebellar atrophy at the time of available brain MRI scans." (PMID 40326640, 2025). "The period of elevated relative ATM expression in these non-A-T specimens coincides with the characteristic and progressive childhood cerebellar atrophy seen in individuals with classic A-T." (PMID 37120494, 2024). "In vivo mouse models for A–T are also not ideal, since ATM-depleted mice do not recapitulate the cerebellar atrophy phenotype." (PMID 37296624, 2023).
cerebellar degeneration (9 papers, 2008 to 2023). Degeneration of the cerebellum. "Overall, these data lead to the hypothesis that cognitive impairments associated with AT are not exclusively generated by cerebellar degeneration, as generally believed, but may also arise from a direct role of ATM in synaptic plasticity." (PMID 37681912, 2023). "It is tempting to speculate that lack of the ATM/AMPK/mitochondrial biogenesis pathway may be a major cause for the progressive cerebellar degeneration in A-T patients." (PMID 18431490, 2008). "In the same study, the authors displayed the ability of ATM to interact in vitro with β-NAP, a neuronal-specific beta-adaptin homolog, identified in a patient with cerebellar degeneration." (PMID 37681912, 2023).
gallbladder cancer (9 papers, 2005 to 2023). "Very little information is available regarding the efficacy of PARPi in BTC patients harboring DDR gene mutations, except for a report demonstrating the clinical benefit of olaparib treatment in a gallbladder cancer patient harboring an ATM inactivating mutation." (PMID 34503215, 2021). "The results underline the importance of expanding the NGS approach in gallbladder cancer in order to propose new molecular markers of predisposition and prognosis exploitable by novel targeted therapies that may improve the response of patients with ATM-deficient cancers." (PMID 33671809, 2021). "For gallbladder cancer, ERBB2 and BRCA2 mutations were significantly more frequent in our cohort, while ATM mutation was enriched in the cBioPortal cohort." (PMID 32373528, 2020). "Likewise, ATM expression can be used as a prognostic marker in breast, gastric, and gall bladder cancers." (PMID 37674118, 2023). "Swift also reported two gall bladder cancers among obligate ATM mutation carriers, but he did not specify the sex of the cases nor present risk." (PMID 15942625, 2005).
HCMV infection (9 papers, 2011 to 2023). "The ataxia-telangiectasia mutated (ATM) kinase pathway that responds to dsDNA breaks is activated following HCMV infection." (PMID 28869497, 2017). "We find that HCMV infection results in a host DNA damage response centered on the Ataxia Telangiectasia Mutated (ATM) protein kinase." (PMID 21589897, 2011). "In conclusion, we demonstrate that expression of UL76 gene induces IL-8 expression as a result of the DNA damage response and that both UL76 and ATM have a role in the mechanism of IL-8 induction during HCMV infection." (PMID 24068928, 2013). "Somewhat surprisingly, we find that the initial accumulation of γH2AX following HCMV infection is dependent on ATM whereas ATM is dispensable for γH2AX accumulation once mature viral DNA replication compartments are formed." (PMID 21589897, 2011). "RL1 might thus prevent SLFN11-mediated repression of ATM/ATR in the presence of the DNA damage response stimulated by HCMV infection in order to benefit viral replication." (PMID 35105802, 2022). "Since it is known that ATM is activated during HCMV infection, targeted degradation of ERC1 could serve as an elegant way to antagonize innate immunity response through attenuation of NF-κB signaling." (PMID 26599541, 2015). "HCMV infection as well as IE1 or IE2 transduction can activate ATM." (PMID 24859341, 2014). "Collectively, these results indicate that during HCMV infection, UL76, and possibly other gene(s), induces IL-8 expression, at least in part, through activation of ATM." (PMID 24068928, 2013). "Many viruses require ATM activation for a fully permissive infection, and it has been reported that ATM is activated by IE1 expression or HCMV infection." (PMID 21589897, 2011). "Thus, ATM and H2AX phosphorylation occur early during HCMV infection and both IE1 and IE2 have the capacity to promote these events." (PMID 21589897, 2011). "This conclusion contrasts with what has been previously reported for HCMV infection, where it was determined that ATM is not required for the progression of HCMV infection." (PMID 21589897, 2011). "In addition to the activation of ATM by IE1, HCMV infection also leads to ATM autophosphorylation." (PMID 37915066, 2023). "Previous studies have shown that ATM signaling is required for efficient HCMV replication, and knockdown of ATM resulted in a similar phenotype as knockdown of ERC1 in our screen, supporting a role for ERC1 in proviral DNA damage signaling during HCMV infection." (PMID 29946045, 2018).
Li-Fraumeni syndrome (9 papers, 2015 to 2025).
liver cancer (9 papers, 2014 to 2026). An epithelial or non-epithelial malignant neoplasm that arises from the liver. "GSEAs of microdissected tumor stroma data sets showed that myoCAF stroma of esophageal, ovarian, colorectal, and liver cancers are enriched for genes associated with the ATM/DDR pathway." (PMID 36353752, 2022). "In sinularin-treated liver cancer (HepG2) cells, Ataxia telangiectasia mutated (ATM)/checkpoint kinase 2 (Chk2) was activated to induce DNA damages in terms of γH2AX." (PMID 29642488, 2018). "While most studies of the anticancer activity of ATM inhibitors focus on the requirement for this protein in the context of DNA repair, we herein found that the antiproliferative effect of Ku on liver cancer cells was associated with the role of ATM as a regulator of mitochondrial function." (PMID 33742560, 2021). "ATM p.R337H mutation was the hotspot site and common in colon and liver cancers." (PMID 28179590, 2017). "This PKI-587/radiation combined treatment inhibits PI3K/AKT/mTOR and homologous recombination (HR) repair-related kinases such as the ATM and the ATM and Rad3-related (ATR) in liver cancer cells." (PMID 36139919, 2022). "Prior work led us to hypothesize that the ATM inhibitor Ku and the AMPK activator phenformin may offer synergistic therapeutic advantages when used to treat liver cancer." (PMID 33742560, 2021).